OSM (oncostatin M)
Diseases named in the same sentence as OSM in open-access papers (continued):
Sharing a sentence is not in itself a finding about the gene and the disease.
osteoarthritis (6 papers, 2017 to 2023). A noninflammatory degenerative joint disease occurring chiefly in older persons, characterized by degeneration of the articular cartilage, hypertrophy of bone at the margins and changes in the synovial membrane. "Inflammatory cytokine stimulation can promote many of the catabolic processes that lead to extracellular matrix destruction in osteoarthritis and oncostatin-M has recently been associated with inflammatory subtypes of osteoarthritis." (PMID 37047586, 2023). "OSM, which belongs to the IL-6 family, is one of the proinflammatory cytokines that contribute to inflammation and cartilage destruction in degenerative arthritis." (PMID 31752879, 2019). "ET‐1 is responsible for inducing oncostatin M expression in osteoarthritis osteoblasts by trans‐activating the oncostatin M gene promoter via the transcription factor Ets‐1." (PMID 28425564, 2017). "OSM expression correlated with disease hallmarks in the acute inflammatory arthritis model, but not in the instability-induced osteoarthritis model, suggesting an association with a more inflammatory phenotype." (PMID 33673583, 2021). "IL-6, Oncostatin-M (OSM), leukemia inhibitory factor (LIF), and other IL-6 family members promote osteoarthritis, either as inflammatory factors or by directly regulating matrix destruction." (PMID 35496642, 2022).
ovarian carcinoma (6 papers, 2020 to 2024). A malignant neoplasm originating from the surface ovarian epithelium. "CD83 highly-associated genes, such as ITGAM, IL1B, CYBB, PIK3R5, BTK, and OSM, ectopically express in ovarian cancer cells or tissues, involving in ovarian cancer progression, hypoxia networks, and the development of chemoresistance." (PMID 32823589, 2020). "Taken together, our findings have provided new insights on the role of OSM-OSMR signaling in promoting cisplatin resistance in ovarian cancer and opportunities to reverse cisplatin-resistant mechanisms in ovarian cancer through targeting anti-OSMR antibodies." (PMID 38839865, 2024). "We characterized that the crosstalk between OSMR and integrins through their interactions with respective ligands like OSM or fibronectin (FN) leads to the activation of STAT3 transcription factor for prolonged period in chemo resistant and highly aggressive ovarian cancer cells." (PMID 38839865, 2024).
periodontitis (6 papers, 2023 to 2025). An acute or chronic inflammatory process that affects the tissues that surround and support the teeth. "A reported molecular mechanism of periodontitis-induced osteopenia involves oncostatin M upregulating the expression of RANKL." (PMID 39894806, 2025). "Periodontitis-induced bone loss was inhibited in osteogenic cell-specific OSMR-deficient mice, demonstrating the in vivo relevance of OSM-mediated neutrophil–osteogenic cell crosstalk." (PMID 38413562, 2024). "Among the cytokines expressed in the periodontal neutrophils, oncostatin M (OSM) potently induced RANKL expression in the primary osteoblasts, and deletion of the OSM receptor in osteogenic cells significantly ameliorated periodontitis-induced bone loss." (PMID 38413562, 2024). "In this study, we demonstrated that the neutrophil–osteogenic cell interaction promotes bone destruction in periodontitis through oncostatin M (OSM)/OSM receptor (OSMR) signaling." (PMID 38413562, 2024). "Nonetheless, some potential biomarkers were noticed in the serum of patients with periodontitis, such as resistin, C-reactive protein, visfatin, oncostatin M, chemokine CXCL10, and proprotein convertase subtilisin/kexin type 9 (PCSK9)." (PMID 37535199, 2023). "One study reported that the periodontitis pathogen Porphyromonas gingivalis (P. gingivalis) exacerbates acute renal inflammation-induced kidney injury through the secretion of gingipain and the modulation of oncostatin M (OSM) expression, which subsequently disrupts renal tight junctions." (PMID 41440335, 2025). "Aydin and Dilsiz reported elevated levels of oncostatin M (OSM), leukemia inhibitory factor (LIF), and IL-11 in the saliva of patients with periodontitis and gingivitis, with levels decreasing following periodontal treatment." (PMID 39410587, 2024).
atopic dermatitis (5 papers, 2019 to 2025). "OSM has been shown to play an important role in regulation of keratinocyte differentiation and down-regulation of expression of epidermal genes in human skin inflammatory disorders, such as atopic dermatitis and psoriasis." (PMID 33004861, 2020). "OSM and OSMR are also overexpressed in the lesional skin of patients with atopic dermatitis, but whether OSM signaling is required for pathogenesis of this condition is unclear." (PMID 31156640, 2019). "Oncostatin M (OSM) is a cytokine that mediates inflammatory processes and is overexpressed in skin lesions of atopic dermatitis (AD)." (PMID 40677708, 2025).
Crohn disease (5 papers, 2022 to 2025). A gastrointestinal disorder characterized by chronic inflammation involving all layers of the intestinal wall, noncaseating granulomas affecting the intestinal wall and regional lymph nodes, and transmural fibrosis. "Of particular interest to us was OSM, as it encodes a cytokine, oncostatin M, that regulates the production of other cytokines and may therefore be a highly relevant master key for the manifestation of inflammatory processes in Crohn’s disease." (PMID 40363705, 2025). "In our analysis, OSM was found to be another gene that is overexpressed in the ileum and colon of patients with Crohn’s disease." (PMID 40363705, 2025). "Our perspective is supported by the fact that oncostatin M has been identified as a predictive biomarker for the outcome of Crohn’s disease." (PMID 40363705, 2025). "In the present investigation, we first identified oncostatin M as a novel target for the treatment of Crohn’s disease." (PMID 40363705, 2025). "Furthermore, we did not only find that the OSM gene was overexpressed in the transcriptome analysis, but also confirmed through immunohistochemistry that oncostatin M protein was expressed in the Crohn’s disease biopsies." (PMID 40363705, 2025). "One study showed that expression of the cytokine oncostatin M is increased in inflamed sites of the mucosa of patients with Crohn’s disease and ulcerative colitis; it also revealed that a high level of oncostatin M expression prior to treatment is associated with the failure of anti-TNF therapy." (PMID 39327633, 2024). "We performed immunohistochemical staining of human colon tissues obtained from healthy individuals and patients suffering from Crohn’s disease and ulcerative colitis, including the ulcerative colitis subgroup of pancolitis, to study whether oncostatin M protein is expressed in colonic tissues." (PMID 40363705, 2025). "Interestingly, humanized anti-OSM antibodies have proven to be safe and well tolerated and are now in phase II clinical trials for the treatment of inflammatory diseases, such as systemic sclerosis and Crohn’s disease." (PMID 35192545, 2022). "In our exploration of the expression of angiogenesis-related genes in Crohn’s disease patients, we found upregulation of OSM, CXCL5, CEACAM3, ISG20, and DUOXA1 genes in Crohn’s disease patients." (PMID 38343536, 2024).
gastric cancer (5 papers, 2007 to 2023). A primary or metastatic malignant neoplasm involving the stomach. "OSM was found to participate in regulating malignant behaviors of multiple tumors including gastric cancer." (PMID 37333017, 2023). "In conclusion, the expression of the OSM gene in the gastric mucosa was higher in early gastric cancer than in precancerous lesions (HGIN and LGIN)." (PMID 31871447, 2019). "This study is the first to detect the expression of OSM in gastric mucosal inflammatory lesions, intestinal metaplasia, dysplasia, and gastric cancer tissues." (PMID 31871447, 2019). "It was recently found that OSM promotes the proliferation, migration, and invasion of gastric cancer cells and that OSM and OSM receptor contribute to GC progression by activating STAT3/FAK/SRC signaling." (PMID 31871447, 2019). "The role of OSM in gastric cancer has yet to be studied, but OSM has been shown to be overexpressed in pre-cancerous lesions and in gastric cancer (GC) when compared to normal gastric tissue, as well as in cancer-derived mesenchymal stem cells isolated from patients." (PMID 37841259, 2023). "The overexpression of OSM contributes to the progression of gastric cancer." (PMID 31871447, 2019).
glioblastoma (5 papers, 2020 to 2025). The most malignant astrocytic tumor (WHO grade IV). "They demonstrated that macrophages induce the MES-like glioblastoma cell state via the macrophage-derived oncostatin M (OSN) and its receptors (OSNR and LIFR) expressed by glioblastoma cells." (PMID 34571910, 2021). "The suppression of the receptor for oncostatin M (OSMR) can prevent glioblastoma cell growth." (PMID 32807793, 2020). "The cytokine receptor for oncostatin M (OSMR) regulates BTSC proliferation and glioblastoma tumorigenesis." (PMID 32807793, 2020).
liver fibrosis (5 papers, 2019 to 2025). "In the mentioned study, liver fibrosis was significantly prevented in OSM knockout mice submitted to the TAA protocol vs related control littermates." (PMID 31861914, 2019). "In order to investigate the involvement of OSM and its receptor OSMβR in NAFLD/NASH progression, mice were fed on MCD or CDAA or HFHF dietary protocols, all able to induce NAFLD progressing to NASH and liver fibrosis." (PMID 31861914, 2019).
lung carcinoma (5 papers, 2013 to 2022). "Experiments performed by Wysoczynski and Ratajczak showed that EVs secreted by lung cancer support angiogenesis by promoting changes in stromal cells, increasing the expression of several pro-angiogenic factors (as IL-8, VEGF, OSM, MMP9)." (PMID 25797265, 2015). "Extracellular vesicles from lung cancer cells can activate the expression of pro-angiogenic factors, including IL-8, VEGF, LIF, oncostatin M, IL-11 and MMP 9 in adjacent stromal cells, “educating” the microenvironment to support lung cancer cell metastasis." (PMID 23908664, 2013). "Furthermore, OSM has been shown to regulate STAT1/3 and STAT5/6 in mouse fibroblasts and is also capable of suppressing cell motility via STAT1 activation in lung cancer." (PMID 31555281, 2019). "Of note, also the expression levels of other putative tumor-derived cachexia-inducing signaling compounds (OSM, LIF, TNFα, IFNγ, PTHrP, ZAG, PIF, TWEAK, IL-1β, MSTN and INHBA) were tested for possible correlation between expression level and prognosis for lung cancer patients." (PMID 28515477, 2017).
pancreatic cancer (5 papers, 2019 to 2024). "Clinically, in patients with pancreatic cancer, high serum levels of IL-6 correlate with poor prognosis, and Oncostatin M (OSM) was overexpressed in the sera of patients with PDAC." (PMID 36495330, 2023). "Moreover, several cancer-related pathways including prostate cancer, integrated pancreatic cancer pathway, and oncostatin M signaling pathway were particularly overrepresented in thermoresistance-associated genes." (PMID 31814876, 2019).
Stroke (5 papers, 2016 to 2023). Sudden impairment of blood flow to a part of the brain due to occlusion or rupture of an artery to the brain. "OSM (oncostatin M), an IL-6 cytokine family member, modulates inflammatory responses and experimental stroke outcomes." (PMID 36691064, 2023). "More recently, the complex role of OSM signaling was further demonstrated by the reported neuroprotective activity of OSM against ischemic stroke, which is dependent on neuronal OSMR-β expression and activation, with decreased neuronal OSMR-β expression leading to worse stroke outcomes." (PMID 27287400, 2016). "Twenty proteins were associated with outcome in univariable models after correction for multiple testing (FDR < 0.05), and for 5 the association was independent of clinical variables, including stroke severity (TNFSF14 [LIGHT], OSM, SIRT2, STAMBP, and 4E-BP1)." (PMID 37794467, 2023).
systemic sclerosis (5 papers, 2020 to 2024). A chronic disorder, possibly autoimmune, marked by excessive production of collagen which results in hardening and thickening of body tissues. "There is currently a clinical trial for a monoclonal antibody against OSM, in patients with systemic scleroderma, which will be discussed in greater detail in Anti-OSM therapeutics." (PMID 37841259, 2023). "While, to our knowledge, no clinical study in KOA has been designed to target OSM, a new generation of anti‐OSM antibody, GSK2330811, was recently developed and tested in a clinical trial for the treatment of systemic sclerosis." (PMID 38111237, 2024). "Another GSK anti-OSM monoclonal antibody, GSK2330811, has entered clinical trials for treatment of systemic scleroderma." (PMID 37841259, 2023).
anemia (4 papers, 2014 to 2025). A reduction in the number of red blood cells, the amount of hemoglobin, and/or the volume of packed red blood cells. "In this issue of the JCI, Garrigue, Kermasson, and colleagues demonstrate that human oncostatin M (OSM) deficiency underlies profound anemia, thrombocytopenia, and neutropenia, unraveling another inherited bone marrow failure syndrome (IBMFS)." (PMID 40091829, 2025). "Interestingly, OSM KO mice showed some characteristics similar to the diagnostics of AA; i.e., fatty marrow, high serum EPO concentration, a high frequency in aged individuals, and anemia." (PMID 25551451, 2014). "Animals lacking the Oncostatin M (OsM) receptor suffer from anemia and EPO stimulation activates OsM in erythroblasts, thereby stimulating osteoclast differentiation." (PMID 40574855, 2025).
autoimmune disease (4 papers, 2017 to 2024). A disorder resulting from loss of function or tissue destruction of an organ or multiple organs, arising from humoral or cellular immune responses of the individual to their own tissue constituents. "The expression of OSM is reportedly upregulated in autoimmune diseases, including RA." (PMID 39080781, 2024).
brain tumor (4 papers, 2020 to 2023). "The cytokine receptor for oncostatin M (OSMR) regulates self-renewing brain tumor stem cells and promotes the resistance of GBM to ionizing radiation." (PMID 33708242, 2021). "The OSMR (receptor for the cytokine Oncostatin M) is a regulator of brain tumor stem cells (BTSC) proliferation by mediating EGFR phosphorylation." (PMID 32725165, 2020). "Studies targeting OSMRβ and STAT3 suggest that a clinical therapeutic that disrupts OSM/OSMRβ/STAT3 signaling can repress brain tumor growth and increase chemoresistance in aggressive brain tumors." (PMID 37841259, 2023).
breast tumor (4 papers, 2014 to 2022). "Single-cell and bioinformatic analysis of murine and human breast tumors revealed that OSM expression was restricted to myeloid cells, whereas OSMR was detected predominantly in fibroblasts and, to a lower extent, cancer cells." (PMID 35192545, 2022). "Increased levels of OSM protein are reported to be concentrated at the invasive edges of breast tumors suggesting a role for OSM in tumor invasion." (PMID 24675570, 2014). "In this paper, we show that OSM, whether acting in a paracrine fashion or produced by breast tumor cells and acting in an autocrine manner, can potentiate preintravasation metastatic events, such as migration, detachment, and increased CTCs." (PMID 29898744, 2018). "Our scRNA-seq and FACS analyses revealed that OSM and OSMR have a unique expression pattern in breast tumors, compared with other members of the IL-6 cytokine family." (PMID 35192545, 2022). "The breast tumor microenvironment (TME) is often saturated with proinflammatory cytokines, such as oncostatin M (OSM), which promote epithelial-to-mesenchymal transitions (EMT) in IDC and increased metastasis." (PMID 34011405, 2021). "Despite the differences between the systems used in our study, our results were consistent in that suppression of OSM reduced metastasis in BALB/c mice and injection of recombinant hOSM or TET-induced hOSM expression in MDATO/OSM cells increased human breast tumor metastasis in athymic mice." (PMID 29898744, 2018).
chronic rhinosinusitis (4 papers, 2021 to 2025). Chronic form of sinusitis. "The elevated mRNA levels of OSM and OSMRβ in conjunction with these specific cytokines underscore the multifaceted nature of chronic rhinosinusitis, implicating OSM as a potential key player in the regulation of inflammatory processes." (PMID 38137445, 2023).
endometrial cancer (4 papers, 2021 to 2026). Primary or metastatic malignant neoplasm involving the endometrium (mucous membrane that lines the endometrial cavity). "Autocrine activation of JAK/STAT3 signal by OSM in ARID1A-deficient endometrial cancer cells promotes PLK1 levels, inducing mitotic abnormality." (PMID 41800254, 2026). "One study reported that 17β-estradiol promotes endometrial cancer proliferation and progression via activation of the IL-6 signaling pathway, and another revealed that OSM, a member of the IL-6 family, enhances endometrial cancer invasion and angiogenesis." (PMID 35036597, 2022). "•Ulipristal acetate induced apoptosis in endometrial cancer cells and activated oncostatin M, IL-6, IL-8 known as proinflammatory cytokine." (PMID 35036597, 2022).
endometriosis (4 papers, 2019 to 2023). The growth of functional endometrial tissue in anatomic sites outside the uterine body. "Additionally, it is worth noting that other IL-6 family proteins (such as ciliary neurotrophic factor (CNTF) and oncostatin-M (OSM)) use the LIF receptor for signaling and have been implicated in various aspects of endometriosis." (PMID 37033980, 2023). "The inflammatory proteins Oncostatin-M (OSM), Monocyte Chemoattractant protein 1 (MCP-1) and TNF Receptor Superfamily Member 9 (TNFRSF9) have been shown to be associated with different symptoms of endometriosis." (PMID 35659226, 2022). "The results of the current study did not suggest that the localization of the endometriosis lesions is related to an altered profile of gut microbiota, in accordance with a recent study concerning potential plasma biomarkers for endometriosis, such as AXIN1, ST1A1, CXCL9, and OSM." (PMID 33660232, 2021). "The proteins AXIN1, ST1A1, CXCL9, and OSM, which showed the greatest differences between endometriosis and controls or symptoms, were not affected by the presence of IBS-like symptoms, localization of endometriosis lesions or hormonal treatment (data not shown)." (PMID 30621017, 2019).
fibrosis (4 papers, 2020 to 2023). the formation of excess fibrous connective tissue in an organ or tissue in a reparative or reactive process. "Among these genes, the expression of inflammation-associated FCER1G, OSM, VEGFA, and ZAP70 was lower in high-grade fibrosis than in low-grade fibrosis, whereas CHIT1 expression, which is associated with fibrogenic activity of macrophages, was higher in high-grade fibrosis." (PMID 35052861, 2022). "Increasingly, we first identified an increased expression of OSM and OMSR in the inflamed colonic tissue of DSS-induced murine chronic UC, which pathologically accounted for the following inflammatory damage, intestinal fibrosis, and immune cells recruitment." (PMID 32332711, 2020).
scleroderma (4 papers, 2013 to 2022). Scleroderma is a rare autoimmune connective tissue disorder characterized by abnormal hardening of the skin and, sometimes, other organs. "Blocking the OSM/OSMRβ pathway or inhibiting the STAT3 pathway could serve as a potential therapy for patients with scleroderma." (PMID 32736577, 2020). "In summary, OSM signaling may play an important role during vessel degeneration and fibrosis in scleroderma." (PMID 32736577, 2020). "The results of RNA-seq also showed that the expressions of cytokines IL-1β and OSM and the key transcription factor IRF7 in scleroderma were down-regulated in GSDMD KO mice." (PMID 35396386, 2022).